SETMAR (SET and mariner transposase domain methyltransferase)
Description:
Protein derived from the fusion of a methylase with the transposase of an Hsmar1 transposon that plays a role in DNA double-strand break repair, stalled replication fork restart and DNA integration. DNA-binding protein, it is indirectly recruited to sites of DNA damage through protein-protein interactions. Also has kept a sequence-specific DNA-binding activity recognizing the 19-mer core of the 5'-terminal inverted repeats (TIRs) of the Hsmar1 element and displays a DNA nicking and end joining activity. In parallel, has a histone methyltransferase activity and methylates 'Lys-4' and 'Lys-36' of histone H3. Specifically mediates dimethylation of H3 'Lys-36' at sites of DNA double-strand break and may recruit proteins required for efficient DSB repair through non-homologous end-joining. Also regulates replication fork processing, promoting replication fork restart and regulating DNA decatenation through stimulation of the topoisomerase activity of TOP2A.
Synonyms: Metnase; Mar1
Tractability: Small molecule: a structure with a bound ligand is known. PROTAC: ubiquitination databases record sites on it; its protein half-life has been measured.
Target class: Writer; Protein methyltransferase; SET domain; Epigenetic regulator
Gene: Protein-coding gene on chromosome 3 (4,303,304 to 4,320,649, forward strand). Ensembl gene ENSG00000170364.
Subcellular location: Nucleus; Chromosome
Subcellular location (Human Protein Atlas): Nucleoli
Gene Ontology:
Molecular function: DNA binding; DNA topoisomerase binding; double-stranded DNA binding; endonuclease activity; histone H3K36 dimethyltransferase activity; histone H3K36 methyltransferase activity; histone H3K4 methyltransferase activity; protein binding; protein homodimerization activity; single-stranded DNA binding; single-stranded DNA endodeoxyribonuclease activity; histone H3 methyltransferase activity; histone methyltransferase activity; nucleic acid binding; protein-lysine N-methyltransferase activity; zinc ion binding
Biological process: cell population proliferation; DNA catabolic process; DNA double-strand break processing; DNA integration; double-strand break repair via nonhomologous end joining; mitotic DNA integrity checkpoint signaling; negative regulation of chromosome organization; nucleic acid metabolic process; positive regulation of DNA topoisomerase (ATP-hydrolyzing) activity; positive regulation of double-strand break repair via nonhomologous end joining; replication fork processing; chromatin remodeling
Cellular component: chromosome; condensed chromosome; nucleolus; nucleus; site of double-strand break; nuclear lumen
Genetic constraint (gnomAD): Loss-of-function variants: 40 observed, 52 expected, observed/expected ratio (o/e) 0.77, 90% interval 0.6 to 1. The upper end of that interval is the gene's LOEUF score, 1, which puts it in group 4 of 6, group 1 being the genes least tolerant of losing a copy. Missense variants: 838 observed, 777.19 expected, observed/expected ratio (o/e) 1.08, 90% interval 1.02 to 1.14. Synonymous variants: 313 observed, 287.46 expected, observed/expected ratio (o/e) 1.09, 90% interval 0.99 to 1.2.
Homologues: Orthologues: chimpanzee SETMAR (99% identical), macaque SETMAR (97% identical). Paralogues in human: GVQW3 (7% identical).